CD34 (CD34 molecule)
Diseases named in the same sentence as CD34 in open-access papers (continued):
Sharing a sentence is not in itself a finding about the gene and the disease.
tumor (continued). "Immunohistochemical staining with CD34, M75/CA-IX and MIB-1 was performed on the rim in the midsection of the tumor to determine respectively MVD, hypoxia and cell proliferation." (PMID 33497385, 2021). "NSG-SGM3 mice were immune-humanized with CD34+ hematopoietic stem cells, followed by engraftment of human ER+ endocrine resistant MBC tumor fragments." (PMID 34717714, 2021). "In hu-CD34+ NSGTM mice implanted orthotopically with the TNBC MDA-MD-231 cell line, HLX10 showed equivalent anti-tumor activity as Pembrolizumab." (PMID 34972111, 2021). "Low CD34 MVD in Notch 1 hot spots and tumor homogeneity on ADC map, which showed correlation with disease recurrence, were contradictory to results of previous studies." (PMID 34642389, 2021). "Histology of tumour revealed a rectal GIST and immunohistochemical staining was positive for CD34 and CD117." (PMID 34659607, 2021). "Tumor cells show an endothelial phenotype, staining commonly positive for CD31, CD34, ERG, and FVIII; a small percentage of cases is reported to express pan-cytokeratins." (PMID 32894473, 2021). "Considering that not only large and mid-sized, but small blood vessels, harbor CD34+ cells within the outermost layer of their wall, adventitial VW-SPCs are omnipresent in vivo this vasculogenic potential might affect the efficacy of anti-angiogenic tumor therapy." (PMID 34359889, 2021). "There were more CD34-positive endothelial cells and fewer α-SMA-positive cells in the tumor area than in the contralateral area, which suggested that there were many immature vessels." (PMID 35083148, 2021). "Immunohistochemistry revealed that the tumor generated from the transplant of GDC40(GFP)CD44 expressed CD44 in almost all tumor cells, whereas CD34‐positive neovascularization was very low compared with the tumor from the transplant of GDC40(GFP)." (PMID 33543833, 2021). "On the other hand, tumor cells were evaluated for the expression of the surface markers CD133, CD44, and CD34." (PMID 37305162, 2021). "CD34+ HSC-derived modified/manipulated DCs have also been clinically investigated in cancer settings with promising outcomes, such as generation of tumor-specific immunity and/or induction of tumor regression in patients with metastatic melanoma." (PMID 34881261, 2021). "Tumor migration and invasion are highly correlated with angiogenesis and EMT process, so Vimentin, E-cadherin, and CD34 were used to evaluate the ability of tumor invasion and migration by IHC." (PMID 33937074, 2021). "To assess the in vivo cytolytic effect of hEND-CD3/BiTE on tumor vascular endothelial cells, we measured the MVD by immunohistochemical staining of endoglin and CD34." (PMID 33995664, 2021). "Compared with the IGF group, the expressions of PCNA, CD34 and PATK in transplanted tumor tissues in the P + IGF group were down-regulated, and the difference was statistically significant (P = 0.000)." (PMID 34323647, 2021). "To confirm the relevance of angiogenesis, we assayed the content of CD34, a canonical marker of angiogenesis, highlighted a strong content in W/DEN tumor samples comparing with CW/DEN." (PMID 33917315, 2021). "As reported in previous studies, the tumor was positive for immunomarkers CD31, CD34, D2-40, CD68, Ki-67 (1–2% positive nuclear staining) as well for smooth muscle markers SMA and Desmine." (PMID 34404967, 2021). "This corresponded to a 0.88 ± 0.03-log PDX-2 tumor cell depletion, which is lower when compared with PDX-1 cells, whereas CD34+ cell and PBPC recoveries were comparable." (PMID 34654486, 2021). "Tumor tissue samples were routinely processed and immunohistochemically stained for Factor VIII, CD31, and CD34." (PMID 34180747, 2021). "Specifically, in samples from patients with high Sokal score and tumour mass, nilotinib intracellular concentration was lower in PMN than in CD34+ cells." (PMID 33731863, 2021).
tumor (continued). "In this study, it was confirmed that CD34+CD38− cells from AML patients possess strong LSC characteristics and tumor formation potential." (PMID 34295821, 2021). "In vitro studies using CD34+/CD38− cells and in vivo murine models demonstrated superior efficacy in the reduction of tumour load in combination with IM than either agent alone." (PMID 33440869, 2021). "OP449, a SET antagonist reactivated PP2A and significantly reduced JAK/STAT5 and PI3K/AKT pathways in vitro CD34+ and K562 CML cells, as well as alleviated tumour burden in vivo xenografted mice with human CML cells." (PMID 33440869, 2021). "The tumor was positive for immunomarkers CD31, CD34, D2-40, CD68, Ki-67 (1–2% positive nuclear staining) as well for smooth muscle markers SMA (Smooth muscle actin) and Desmine." (PMID 34404967, 2021). "Histological features were evaluated and revealed a highly cellular tumor with positive expression of BCL2, CD34, CD99, and STAT6 proteins that are consistent with a diagnosis of SFT." (PMID 34765368, 2021). "Our tumor MSCs expressed the following surface antigens: CD73, CD90, CD105, and HLA-class I ≥95% and CD34, CD14, CD45, CD31, and HLA-DR ≤ 5%." (PMID 34805051, 2021). "The tumor cell immunophenotype was positive for vimentin, EMA and negative for CK-pan, TTF-1, CAM5.2, S-100, calponin, SMA, desmin, ALK, CD31 and CD34." (PMID 32039736, 2020). "The results of immunohistochemical investigation revealed that tumor cells stained positive for CD31, CD34, VI antigen, and vimentin which confirmed the endothelial origin of the tumor." (PMID 31906980, 2020). "We isolated the cells from neoplasm and compared different bio-markers (CD90, CD105, CD29, CD14, CD34, CD45) between three patients’ GCTSCs and normal bone marrow MSCs." (PMID 32904108, 2020). "Well in line with histology, the tumor showed expression of both glial (e.g. GFAP) and neuronal markers (e.g. synaptophysin) with pathological expression of CD34 and retained ATRX expression." (PMID 32451719, 2020). "Tumor samples in the present study had been stained for markers including NUT, P63, P40, TTF-1, keratin, CK7, Syn, CD56, CgA, CD34, CD117, EGFR, and Ki-67." (PMID 32149149, 2020). "Immunohistochemical staining revealed that the tumor cells were positive for STAT6, CD34, CD99, and BCL2." (PMID 32638177, 2020). "The expression of mRNA and protein (VIM, ALP, CK14, CD34, OPN) in the MUPS‐1 cells matched the expression in the primary tumor confirming the origin of our cell population." (PMID 32652895, 2020). "When mice with subcutaneously transplanted TEB and engrafted with human CD34+ HSCs were 11 weeks later injected orthotopically with human MDA-MB-231BO metastatic TNBC cells, formation of primary tumor and metastases to hTEB was observed." (PMID 32570871, 2020). "As SNU484 robustly establishes the tumor in the orthotopic model than Hs746T (100% vs. 50%) with the heterogeneous enhancement on T2 MRI, we focused on SNU484 cells which expressed CD34 gene higher than other cell lines." (PMID 32293340, 2020). "The human immune system in animals can be reconstructed using CD34+ HSCs or PBMCs, which makes it possible to obtain the most accurate PDX models in which the tumor and immune components are obtained from the same donor." (PMID 32526987, 2020). "Tumor cell proliferation was evaluated by immunostaining for PCNA, and angiogenesis was evaluated by immunostaining for CD34." (PMID 32256354, 2020). "Immunohistochemically, the tumor cells exhibit strongly and diffusely positive cytoplasmic expression of CD34 and nuclear STAT6 expression; however, the expression of CD34 and STAT6 is frequently lost in dedifferentiated SFT." (PMID 32867125, 2020).
tumor (continued). "As for immunohistochemistry, all neoplasms stained positively for CD1a, CD207 (Langerin) and S100; inconstant was the stain for CD34 and CD68 (approximately 60%)." (PMID 32825016, 2020). "The aim of this study was to explore the potential value of assessing the expression of ELTD1, CD34 and VEGFR2 in tumor vessels to predict benefit of sunitinib treatment in mRCC patients." (PMID 32321460, 2020). "Immunohistochemistry revealed that the tumour was positive for KIT and CD34, and GIST was diagnosed." (PMID 32283516, 2020). "The diagnosis of EHE was based on the bony destruction as seen in x-rays and in the accumulation of tumor cells that were 100% positive to CD31; CD34 and ERG to endothelial markers." (PMID 33158420, 2020). "In our study, tumor growth curves of xenografts were analyzed to confirm that in the early stages of tumorigenesis, BMPER was highly expressed, while CXCL10, HOXA9, and CD34 were lowly expressed." (PMID 32432046, 2020). "The vasculature in tumors is generally analyzed by the quantification of the microvessel number or area found within the tumor through immunohistochemical analysis after staining common EC markers such as CD31 and CD34." (PMID 32375250, 2020). "Immunohistochemical staining indicated that tumor cells were positive for CD31, CD34, ERG, PCK, FLi-1, TFE-3, and Ki67 (labeling index, 5–15%)." (PMID 33121478, 2020). "In the late-tumor growth stage, BMPER, CXCL10, and HOXA9 were all lowly expressed, while CD34 was highly expressed." (PMID 32432046, 2020). "The tumor cells are occasionally positive for cytokeratins (CKs) and express vascular markers such as CD31, CD34, and factor VIII related antigen." (PMID 32977811, 2020). "Currently, the gold standard in humanising the immune system of mice involves the implantation of cord blood-derived CD34+ cells into previously gamma-irradiated NSG mice, which is the most accepted mouse strain for xenotransplantation and tumour modelling." (PMID 32781703, 2020). "By immunohistochemistry, tumor cells were positive for CD31, CD34, ERG, PCK, FLi-1, TFE-3, and Ki-67 (labeling index range, 5–15%)." (PMID 33121478, 2020). "The main differential diagnosis of this LMNA-NTRK1 fusion tumor was IMT because of prominent inflammatory cells in the tumor, but it can be ruled out based on its immunoprofile (SMA-negative, with S100/CD34 coexpression)." (PMID 32957984, 2020). "Immunohistochemically, the tumor cells are positive for vascular markers (e.g., CD31, CD34, FLI1, and ERG)." (PMID 32316685, 2020). "K562-IR cells are CD34-/CD38-, BCR-Abl-independent, proliferate slowly, highly adherent and form intact tumor spheroids." (PMID 32106243, 2020). "Immunohistochemical staining with endothelial markers CD31, CD34, and ERG was positive for 100% of the tumor cells, and reaction with the epithelial marker PanCK was positive for 10% of the tumor cells." (PMID 33158420, 2020). "CD34 and CD31+ spindle tumor cells were detected, and the high-grade tumor cells had a high Ki67 index score of 80%." (PMID 32337612, 2020). "Meanwhile, the key components of the bone marrow niche, mesenchymal stem cells (CD45-Lin-CD34-c-kit-CD29+) and CXCL12 producing cells, were significantly decreased in the bone marrow of tumor-bearing mice." (PMID 33603745, 2020). "The expression of Ki67 in the xenografted tumor tissues was further determined by immunohistochemistry and the MVD was calculated by detecting CD34." (PMID 32714856, 2020). "The tumour cells were positive to vimentin and CD68, and negative to desmin, SMA, S100 protein, EMA, cytokeratins AE1/AE3, CD117, and CD34 antibodies." (PMID 31773099, 2019). "Tumour slides from EC patients were stained by immunofluorescence for carbonic anhydrase IX (CAIX) as hypoxic marker and CD34 for assessment of microvessel density (MVD)." (PMID 31011231, 2019).
tumor (continued). "CD34/PAS staining indicated that VM was significantly increased in the OE-Gal-1 group, and immunostaining showed positive vimentin staining in both the tumor stroma and tumor cells, while E-cadherin staining was negative in those samples." (PMID 31772662, 2019). "After the tumor-bearing mice were sacrificed, Ad-ING-IL-24 treated xenograft tumors featured a reduction of CD34, as measured by immunohistochemistry." (PMID 31390718, 2019). "Meanwhile, this meta-analysis suggests that postoperative detection with CD34- and/or CD31- of VM+ tumor samples in MM would be useful in finding critical therapy targets as well as for making better follow-up plans." (PMID 31752759, 2019). "In non-tumour haematopoietic control cells (CD133+HSC and CD34+HSC), all polyphenols antagonised the action of all alkylating agents, significantly increasing both ATP levels and cell survival (P ≤ 0.05)." (PMID 31360305, 2019). "CD34 and PAS double staining showed that the VM formation in the tumor was less in the melittin treatment groups than that in control group." (PMID 31057657, 2019). "The final diagnosis of KS was made on excision biopsy as tumor cells were positive for HHV8, LANA-1, CD34 & CD31." (PMID 31827596, 2019). "In this paper, experiments in-vivo showed that at doses of 50, 100, and 200 mg/kg, GBEE reduced the expression of CD34 protein in vascular endothelial cells and made MVD decreased with a dose-dependent manner in B16 transplanted tumor tissues." (PMID 31531063, 2019). "The common markers of CSCs are CD34+CD38− for AML, and CD133+, CD44+, and others for solid tumors, as these cells display higher abilities of tumor ignition in nude and NOD/SCID mice." (PMID 31336602, 2019). "Histologic examination revealed epithelioid/spindle tumor cells with oval nuclei, which were positive for CD117, DOG1, and CD34." (PMID 31590135, 2019). "Consistent with tumor growth inhibition, the result showed that in tumors with depleted LPCAT1 the expression of PCNA, CD34 and MMP9 were diminished (P < 0.05)." (PMID 30791942, 2019). "CD34, Bcl-2, and CD99 have been recognized as a representative marker of SFT, but they can also be positive in other neoplasms." (PMID 31520184, 2019). "Antibodies used to visualize endothelial cells differ amongst studies (CD31, CD34, factor VIII, miRNA-126), and sampling of the measurement area within the tumour is another critical factor." (PMID 31420015, 2019). "This phenotype was clearly recapitulated in AKT/YapS127A murine CCA, as demonstrated by CD34 immunostaining, showing that endothelial cells were predominantly located in the outer layers of CCA tumor nodules." (PMID 30741922, 2019). "In independent clones from the THP‐1–derived tumors, similar results were confirmed in tumor growth and Ki‐67‐, TUNEL‐ and CD34‐staining." (PMID 30843660, 2019). "The tumor cells showed diffuse, strong immunoreactivity for STAT 6, CD 99, CD34, BCL-2 and Vimentin." (PMID 30508695, 2019). "Unlike numerous studies reporting that CD34 and VWF are involved in angiogenesis, our study shows that CD34 and VWF expression coincide with reduced tumor vasculature." (PMID 31803626, 2019). "IHC assays on the tumor tissues of orthotopic tumor implantation mice also revealed that CD31-positive and CD34-positive ECs significantly decreased in CLEC3Bhigh xenografts." (PMID 31477130, 2019). "Of note, the tumor was abundantly vascular, with strong immunostaining for smooth muscle actin (SMA), CD31, and CD34." (PMID 30263099, 2018). "Immunohistochemistry of the tumours in this series showed a more or less consistent positivity for GFAP, S100, NSE and CD34 with a significant Ki67 expression." (PMID 30774826, 2018). "After 7 h, cells were stained with tumor specific markers (e.g., CD9, CD34) and tumor viability was analyzed by flow cytometry using 7AAD and Annexin V staining." (PMID 30233577, 2018).
tumor (continued). "CD34 and VEGF-3 levels in primary tumors collected from Hca-P-ANXA5-shRNA1- and Hca-P-ANXA5-shControl-transplanted mice on 10th (soon after tumor formation) and 21st d were compared by IHC assay." (PMID 29802377, 2018). "To evaluate the involvement of Rab11-FIP2 in tumor angiogenesis of CRC clinically, we used immunohistochemical staining for CD34 in 28 human CRC tissue samples and calculated the number of CD34-positive microvessels in the tumor area." (PMID 29540997, 2018). "Moreover, because CD31/CD34 staining is specific to studying microvessels, IHC-stained images are rarely available in any existing public datasets, such as The Cancer Genome Atlas (TCGA), which greatly hinders research into the role of microvessels in tumor progression and response to treatment." (PMID 29482496, 2018). "Moderate to strong cytoplasmic staining in more than 10% tumor cells was considered positive for ASMA, S100 and CD34." (PMID 29996918, 2018). "The tumor cells were diffusely positive for factor XIIIa and ALK, but were negative for AE1/AE3 keratin, alpha-smooth muscle actin, CD30, CD34, CD68, PU.1, melan A, MITF, and S-100 protein." (PMID 29747676, 2018). "The expression of markers of hypoxia (HIF2α), angiogenesis (VEGF), tumor microvascularity (CD31, CD34, vWF, CD105), and proliferation (Ki-67) were assessed immunohistochemically (IHC)." (PMID 29662659, 2018). "H&E staining and immunofluorescence staining of CD34 showed that PARK2 reduced the number of hematocytes in the plugs and decreased the tumor microvessel density in the Matrigel plugs." (PMID 29515107, 2018). "Multicolor immunofluorescence staining (IF staining) showed that many ETV2+ tumor cells were preferentially arranged as vascular-like clusters, notably co-expressing CD31 and CD34." (PMID 29527330, 2018). "We have investigated the potential for off-tumor, on-target effects of the novel CAR33VH on peripheral blood CD34+ hematopoietic stem cells in a colony forming assay." (PMID 30524966, 2018). "It indicated that CD34 had an improved sensitivity and specificity than factor VIII for endothelial cells activated by regional tumor angiogenesis." (PMID 30305802, 2018). "In order to generate a consistent ROR1+ tumor model in huNSG mice, we have to improve the transduction efficiency of CD34+ cells and achieve a higher engraftment of TCL-1-transduced CD34+ cells." (PMID 29850623, 2018). "Nevertheless, the tumor demonstrated strong immunoreactivity for STAT6, thereby indicating SFT, whereas CD34 was only weakly expressed." (PMID 30168002, 2018). "We also confirmed that RAC2 is co-expressed with CD34-positive cells and that RAC1 is strongly expressed at the tumor-stroma border of Tgfbr2 cKO SCC." (PMID 28219480, 2017). "The levels of CD34 and HIF-1α in the tumour and para-tumour groups and in the tumour and normal groups are significantly different." (PMID 29072683, 2017). "Here, we present a case report of a 60-year-old female with a 5-cm tumor in the inferior vena cava (IVC) that was positive for c-kit and CD34 expression." (PMID 28421549, 2017). "In fact, in the single tertiary tumor that formed after transplant of CD34− SCC cells, CD34 was re-expressed in 49% of YFP+ epithelial tumor cells by FACS, indicating that CD34 expression is dynamic in vivo." (PMID 28219480, 2017). "The immunohistological findings showed that the tumor cells stained negatively with S100 and SMA and positively with c-kit and CD34; the tumor was diagnosed to be a KIT-positive GIST." (PMID 28058590, 2017). "Tertiary anorectal tumors maintained the tumor hierarchy of the primary and secondary Tgfbr2 cKO SCC, and selection for CD34+ CSCs resulted in an increased ratio of CD34+ cells (75%)." (PMID 28219480, 2017). "Overall, the BRC cases analyzed had larger numbers of CD34+ tumor stromal vessels per TMA core (mean 11; range 0–45) as compared to VEGFR2+ tumor stromal vessels per TMA core (mean 3.4; range 0–20)." (PMID 28533703, 2017).